PTK2 (protein tyrosine kinase 2)
Diseases named in the same sentence as PTK2 in open-access papers (continued):
Sharing a sentence is not in itself a finding about the gene and the disease.
pancreatic cancer (147 papers, 2005 to 2026). "The phosphorylation of PTK2 was highly associated with CMG2 expression in the three pancreatic cancer cells that were examined in the present study." (PMID 39199664, 2024). "Using the TCGA and GTEx databases, we investigated the genetic alterations and mRNA expression levels of PTK2 (the encoding-gene for FAK) in normal pancreatic tissue and pancreatic cancer and its impact on patient survival." (PMID 32705304, 2021). "Using cBioportal, we examined the TCGA, PanCancer atlas cohort, which included 168 pancreatic neoplasms samples with complete PTK2 mutations and expression data from a total of 184 patients originally in the cohort." (PMID 32705304, 2021). "Several studies also showed that silencing of PTK2 can render pancreatic cancers responsive to anti-PD153." (PMID 35013211, 2022). "The PTK2, also known as FAK, upregulation of its expression could accelerate progression and contribute to an immunosuppressive environment of pancreatic cancer." (PMID 35712127, 2022). "FXR was significantly increased in pancreatic cancer cell lines in comparison to normal pancreatic cells and FXR was found as the regulator of FAK (PTK2, protein tyrosine kinase 2)/c-Jun (JUN, Jun proto-oncogene, AP-1 transcription factor subunit) / MUC4 (mucin 4) signaling pathway." (PMID 31379749, 2019).
lung carcinoma (145 papers, 2005 to 2026). "To verify the functional association, we generated PTK2-knockout (PTK2-KO) lung cancer cells by using CRISPR-Cas9 gene editing method, and performed in vitro cancer progression assay, including 3D tumor spheroid assay, and in vivo xenografted NSG (NOD/SCID/IL-2Rγnull) mouse assay." (PMID 38816856, 2024). "Elevated expression of PTK2 has been documented in various malignancies such as lung cancer, hepatocellular carcinoma, and lymphocytic leukemia." (PMID 40873580, 2025). "This study provides a theoretical basis for the therapeutic intervention of PTK2 targeting EGFR- or TLRs-induced lung cancer progression." (PMID 38816856, 2024). "The expression pattern of circRNAs HIPK3 and PTK2 was determined using quantitative polymerase chain reaction (qPCR) in lung cancer patient samples and cell lines." (PMID 34326381, 2021). "PTK2 expression has been explored in several human epithelial cancers including breast, ovarian, colorectal, and lung cancers." (PMID 31791326, 2019). "Here, we find one disease-associated microRNA-target pair with a common phenotype: both the host gene PTK2 and its intronic microRNA miR-151 are annotated with lung cancer in KEGG DISEASE and PhenomiR, respectively." (PMID 20614023, 2010). "Finally, therapeutic effects targeted to PTK2 in lung cancer in response to EGF and TLR agonists were verified by using its inhibitor (Defactinib)." (PMID 38816856, 2024). "In summary, we identified that up-regulated PTK2 might be a reliable marker for EGFR- or TLRs-induced lung cancer progression in NSCLC patients via the regulation of the cross-talk between EGFR- and TLRs-mediated signaling." (PMID 38816856, 2024). "Protein tyrosine kinase 2 (PTK2) expression has been reported in various types of human epithelial cancers including lung cancer; however, the role of PTK2 in epidermal growth factor receptor (EGFR)-mutant non-small cell lung cancer (NSCLC) has not been elucidated." (PMID 31791326, 2019). "In this study, the potential targets of Pinellia ternata highly overlap with lung cancer pathological genes, with FGFR4, CDK2, JAK2, KDR, PAK4, PTK2 and PDGFRA being the core." (PMID 42149884, 2026). "PTK2, PGF, SLCO4A1 and Cdc27 are among the genes in Merged-module whose over-expression has been reported in different cancers including lung cancer and we have shown it as well." (PMID 23874428, 2013).
glioma (118 papers, 2008 to 2025). A benign or malignant brain and spinal cord tumor that arises from glial cells (astrocytes, oligodendrocytes, ependymal cells). "PTK2, encoding FAK, has been confirmed to mediate protective autophagy in anoikis-resistant glioma stem cells." (PMID 32977843, 2020). "Similarly, the protective association of PTK2 raises intriguing questions about its context-dependent functions in glioma that warrant further investigation for potential therapeutic exploitation." (PMID 41356219, 2025). "Conversely, the protective associations observed with PTK2, CCND2, RAD51L3-RFFL, and MAX suggest potential compensatory or tumor-suppressive functions in glioma." (PMID 41356219, 2025). "Consistent with the previous results, ITGA5 protein levels were significantly increased in glioma compared to peritumor tissue, whereas PTK2 levels were decreased in tumors." (PMID 36091049, 2022). "Several genes (i.e. ITGB5 and PTK2) in the glioma invasiveness signaling are over-expressed for the invasion and migration of glioma cells in the CNS cell lines." (PMID 23937249, 2013). "Immunohistochemistry (IHC) staining was performed to detect the representative PTK2 and ITGA5 protein levels in gliomas and peritumor tissues (16 cases) obtained from patients treated at The Second Hospital of Shandong University." (PMID 36091049, 2022). "LncRNA AC004943.2 may contribute to tumor progression through regulation of the miR-135a-5p and PTK2/PI3K axis, while SOX21-AS1 enhances glioma cell proliferation and invasion by sponging miR-144-3p to upregulate PAK7 expression." (PMID 40661083, 2025).
glioblastoma (108 papers, 2007 to 2025). The most malignant astrocytic tumor (WHO grade IV). "In glioblastoma cells, high PTK2 expression can increase the expression of CCND1 and CCNE, reduce the expression of CDKN1B (p27Kip1) and p21Waf1, and enhance the activity of CDK4, thereby promoting the G1/S phase transformation of glioblastoma cells." (PMID 36770809, 2023). "Kaplan–Meier analysis of 619 glioblastoma cases from the glioblastoma tumor RNA-Sequence dataset identified a negative association between levels of gene expression of PTK2 and PTK2B and overall survival." (PMID 37686276, 2023). "Additionally, immunohistochemical analysis of most anaplastic astrocytomas and glioblastomas demonstrated a strong expression of the PTK2 protein." (PMID 37370767, 2023).
hepatocellular carcinoma (107 papers, 2005 to 2026). A malignant tumor that arises from hepatocytes. "For example, sorafenib resistance in hepatocellular carcinoma is caused by protein tyrosine kinase 2 (PTK2) promoter hypomethylation, which also causes PTK2 overexpression and stimulates the signaling pathway of Wnt." (PMID 41431719, 2026). "As a prototypic oncogene, PTK2 can regulate cancer stem cells to enhance the tumorigenesis of hepatocellular carcinoma." (PMID 36533074, 2022). "In hepatocellular carcinoma, the activation of the Wnt signaling pathway, induced by protein tyrosine kinase-2 (PTK2), boosted CSC tumorigenic potential and contributed to sorafenib resistance." (PMID 36498571, 2022). "PTK2 is a signaling molecule that can promote cell motility and its expression has been reported to be coordinated with miR-151 in hepatocellular carcinoma tissue samples." (PMID 24548287, 2014). "Additionally, HCC patients with ETV1/PTK2 or ETV1/c-MET co-positive hepatocellular carcinoma in two different cohorts had a worse prognosis." (PMID 36407100, 2022). "Moreover, the expression of PTK2 genes in hepatocellular carcinoma is inversely correlated with its promoter methylation level." (PMID 36533074, 2022). "In addition, PTK2 is overexpressed in many major cancer types, including lung cancer, hepatocellular carcinoma, and lymphocytic leukemia." (PMID 36533074, 2022). "By directly increasing PTK2 and IGF1R in hepatocellular carcinoma cells, BACH1 speeds up the development and spread of Hepatocellular carcinoma (HCC)." (PMID 36407100, 2022). "Human hepatocellular carcinoma (HCC) cells overexpress focal adhesion tyrosine kinase (PTK2)." (PMID 34277564, 2021). "In hepatocellular carcinoma (HCC), BACH1 upregulates the expression of cell motility-related genes, such as insulin-like growth factor 1 receptor (IGF1R) and protein tyrosine kinase 2 (PTK2), to facilitate the growth and metastasis of HCC." (PMID 38321558, 2024).
gastric cancer (95 papers, 2011 to 2025). A primary or metastatic malignant neoplasm involving the stomach. "Hub genes containing COL5A2, JAG1, TIMP1, FGFR1, PDFGA, VEGFA, and PTK2 were collected from the gene sets and were proven to be linked to the occurrence and development of gastric cancer." (PMID 35875363, 2022). "In gastric cancer, PTK2 amplification is positively associated with age, tumor size, metastasis, and invasion." (PMID 31791326, 2019). "In addition, owing to amplification processes of the encoding PTK2 gene (on chromosome 8, in humans), FAK is overexpressed in several human tumors, such as gastric cancer and colorectal cancer." (PMID 39281374, 2024). "Cyclic RNA PTK2 can accelerate the proliferation of gastric cancer cell and inhibit apoptosis via miR-139-3p26,27." (PMID 37031243, 2023). "The present study showed that the ptk2 gene expression and the frequency of gastric cancer increase along with increasing age (P < 0.001)." (PMID 36060520, 2022). "The study indicates that inhibition of CAMKK2 has an anti-oncogenic effect in gastric cells regulating phosphorylation of STAT3 through PTK2/c-JUN in gastric cancer." (PMID 35646067, 2022). "Our data provide a glimpse of CAMKK2-regulated tyrosine signaling in gastric cancer cells, which involves the PTK2/JUN/STAT3 axis." (PMID 35646067, 2022). "This study investigated the correlation between the H. pylori virulence genes and ptk2 and mt2a genes expression in gastric antral epithelial cells of gastritis and gastric cancer patients with H. pylori infection." (PMID 36060520, 2022). "This means that the ptk2 gene expression in gastric antral epithelial cells increases with getting older and gastric cancer up 2.51 and 4.32 times, respectively (P < 0.005)." (PMID 36060520, 2022). "In this study, we identified a cancer-associated circRNA, circPTK2, originating from exons 27, 28, and 29 of its host gene PTK2, and found that circPTK2 was significantly downregulated in gastric cancer tissues." (PMID 34604044, 2021). "We found that TLN1 may influence prognosis of gastric cancer through the PTK2-PXN-VCL-E-Cadherin-CAPN2-MAPK1 signaling pathway." (PMID 40104507, 2025). "A more detailed understanding about the role of CAMKK2 in activation of the tyrosine phosphoproteome and, in particular, PTK2/JUN/STAT3 signaling in gastric cancer is needed, in addition to functional studies in preclinical models, which is beyond the scope of this article." (PMID 35646067, 2022). "This indicates that CAMKK2-mediated signaling may orchestrate through PTK2/JUN/STAT3 signaling in gastric cancer." (PMID 35646067, 2022). "We have reported decreased phosphorylation of TYK2 at Y292, PTK2 at Y662, and STAT3 at Y705, Y737 upon inhibition of CAMKK2 in gastric cancer cells." (PMID 35646067, 2022). "PTK2 is also reported to activate STAT3 and is overexpressed in multiple cancers such as gastric cancer." (PMID 35646067, 2022). "Our western blot data revealed decreased phosphorylation of PTK2 at Y925, p-c-JUN at S73, STAT3 at Y705, and AMPK at T172 upon both inhibition and silencing of CAMKK2 in gastric cancer." (PMID 35646067, 2022). "Our data revealed decreased phosphorylation of PTK2, c-JUN, and STAT3 upon inhibition and siRNA-mediated silencing of CAMKK2 in gastric cancer cells." (PMID 35646067, 2022). "Accordingly, KCNMA1 overexpression was not sufficient to inhibit the migration and invasion of gastric cancer cells after PTK2 knockdown." (PMID 30791468, 2019). "Similarly, inhibitory ability on gastric cancer cell migration and invasion was also attenuated by si-PTK2, that is, KCNMA1 did not have the ability to suppress migration and invasion of gastric cancer cells after PTK2 was knockdown." (PMID 28231797, 2017).
colon carcinoma (93 papers, 2005 to 2026). "It is found that PTK2 is associated with the sensitivity of colon cancer cells to DNA damage therapy." (PMID 30275981, 2018). "Early studies evaluating FAK levels in human tumor cell lines noted that several lung, breast and colon carcinoma cells exhibited FAK gene (PTK2) gains." (PMID 39034922, 2024). "Interestingly, PTK2 has been shown to be overexpressed in metastatic human breast and colon cancers." (PMID 34439361, 2021). "In colon cancer, FAK phosphorylation enhanced the activity of the transcription factor NANOG, which activated PTK2 to initiate the NK-κB pathway to support the progression of carcinoma cells." (PMID 39895788, 2025). "SPHK1 regulates the PTK2/FAK (protein tyrosine kinase 2) pathway and activates the EGFR (epidermal growth factor receptor) pathway to confer tumour metastasis in colon cancer and oesophageal cancer." (PMID 34857818, 2021).
prostate carcinoma (92 papers, 2003 to 2026). A carcinoma that arises from epithelial cells of the prostate gland. "Further studies have found that in DU145 and PC-3 prostate cancer cells, menthol inhibits cell motility by inhibiting the phosphorylation of protein tyrosine kinase 2 (PTK2) through the TRMP8 pathway." (PMID 37007039, 2023). "RhoC has also been shown to activate the Protein-Tyrosine Kinase 2 (PYK2) pathway in prostate cancer, consequently leading to metastasis in prostate cancer." (PMID 31340863, 2019).
colorectal cancer (77 papers, 2012 to 2026). A primary or metastatic malignant neoplasm that affects the colon or rectum. "In summary, we reported that increased expression levels of hsa_circ_0005273, spliced from the pre-mRNA PTK2, was involved in the metastasis of colorectal cancer via physical binding to phosphorylation sites Ser38, Ser55 and Ser82 of vimentin." (PMID 31973707, 2020). "PTK2 has been shown to be gained in prostate, gastric, colorectal cancers and in salivary adenoid cystic carcinoma." (PMID 29050216, 2017). "In addition, they identified that HNF4G targets G protein gamma 12 (GNG12) and protein tyrosine kinase 2 to activate the phosphatidylinositol 3-kinase/protein kinase B (PI3K/AKT) pathway and enhance cell proliferation in colorectal cancer (CRC) (PTK2)." (PMID 37205191, 2023). "PTK2 amplification in ovarian, head and neck, breast, and colorectal cancer may account for its overexpression in these tumors." (PMID 31791326, 2019). "In addition, mRNA expression (RNAseq) of the PTK2 gene encoding the FAK protein provided by the Cancer Cell Line Encyclopedia database supports strong evidence of FAK overexpression in colorectal cancer." (PMID 31501460, 2019). "HNF4G is overexpressed in colorectal cancer (CRC) and promotes CRC cell proliferation via the PI3K/AKT pathway by targeting G protein subunit gamma 12 (GNG12) and protein tyrosine kinase 2 (PTK2)." (PMID 35240026, 2022).
non-small cell lung carcinoma (49 papers, 2015 to 2025). A group of at least three distinct histological types of lung cancer, including non-small cell squamous cell carcinoma, adenocarcinoma, and large cell carcinoma. "By using microarray data of non-small cell lung cancer (NSCLC) tumor tissues and matched normal tissues of 42 NSCLC patients, the genetic and clinical associations between PTK2, EGFR, and TLRs were analyzed in NSCLC patients." (PMID 38816856, 2024).
osteosarcoma (45 papers, 2010 to 2025). A usually aggressive malignant bone-forming mesenchymal neoplasm, predominantly affecting adolescents and young adults. "AURKB is a serine/threonine kinase that has been proposed to stimulate the invasion and proliferation of osteosarcoma through PTK2/PI3K/AKt/NF-κB signaling pathway and VCP." (PMID 33858425, 2021). "Experimental validation of predicted miRNA targets revealed an increase in the expression of focal adhesion kinase (PTK2) genes, implicating EV-mediated miRNA transfer in high grade, aggressive osteosarcomas, in agreement with previous observations." (PMID 27812189, 2016). "RT-PCR validation of predicted miRNA targets revealed an increase in the expression of matrix metalloproteinase (MMP1) and focal adhesion kinase (PTK2), implicating EV-mediated miRNA transfer in high grade, aggressive osteosarcomas, in agreement with previous observations." (PMID 27812189, 2016). "In this study we demonstrate in human osteosarcoma (U2OS) and rat kangaroo kidney epithelial cells (PtK2), that ablation of the centrosome results in the loss of the cell's ability to maintain a polarized microtubule network necessary for cell migration in a specific direction." (PMID 21203421, 2010). "SPON1 upregulation is closely related to metastasis and progression of osteosarcoma, promoting migration and invasion of osteosarcoma cells in vivo and in vitro, as well as activating FAK (PTK2) and SRC in osteosarcoma cells." (PMID 36520032, 2023). "The loss of directed migration in two different types of cells from widely different species (PtK2, marsupial long-nosed rat kangaroo kidney cells, and U2OS, human osteosarcoma cells) suggests that the role of the centrosome in polarization may be conserved." (PMID 21203421, 2010).
squamous cell carcinoma (42 papers, 2005 to 2025). A carcinoma arising from squamous epithelial cells. "In fact, copy number gains of PTK2 are frequent in cell lines derived from invasive epithelial tumors, and PTK2 amplification correlates with increased protein expression in squamous carcinoma cell lines." (PMID 16457699, 2005).
breast tumor (40 papers, 2005 to 2025). "SMARCE1-mediated PTK2 activation likely plays a key role in promoting metastasis of basal-like and luminal B subtype of breast tumors." (PMID 27495308, 2016). "Next, we examined the relationship between the expression of SMARCE1 and PTK2 in breast tumors in The Cancer Genome Atlas (TCGA) database." (PMID 27495308, 2016). "In addition, the screening of NCI-60 panel cells, including breast tumor cells, by a modified real competitive PCR (mrcPCR), has allowed the identification of PTK2 among the drug-target genes characterized by copy-number gain." (PMID 33562737, 2021). "Expression data analysis of a large cohort of human breast tumors revealed that high expression of SMARCE1 or PTK2 is associated with poor prognosis and tumor relapse, and PTK2 expression is positively correlated with SMARCE1 expression in basal-like and luminal B subtypes of breast tumors." (PMID 27495308, 2016). "Our findings are likely relevant to basal-like and luminal B breast tumors, because a positively correlated expression between SMARCE1 and PTK2 is evident in these subtypes of tumors." (PMID 27495308, 2016).
mesothelioma (40 papers, 2014 to 2026). A usually malignant and aggressive neoplasm of the mesothelium which is often associated with exposure to asbestos. "Another mechanism regarding the actions of PGRN covers the formation of protein tyrosine kinase 2 (PTK2) and paxillin (PXN) complex through ERK1/2 activation that promotes cell invasion and migration, as observed in bladder cancer and mesothelioma." (PMID 38247816, 2024).
metastatic tumors (40 papers, 2008 to 2025). "We found that PTK2 showed differing associations: in metastatic tumors, it correlated positively with MHC, SC and CP, and negatively with EC and AZ, while in primary tumors, it was positively correlated with MHC and SC, but its correlations with AZ were mixed." (PMID 40943183, 2025).